CD1D (CD1d molecule)
Diseases named in the same sentence as CD1D in open-access papers (continued):
Sharing a sentence is not in itself a finding about the gene and the disease.
coeliac disease (1 paper, 2013). "However our observations agree with those of Grose and colleagues, who found that Va24+ T cells, Va24 + /Vb11+ T cells and α-GalCer/CD1d tetramer+ iNKT cells were numerically deficient and functionally impaired in coeliac disease." (PMID 24124528, 2013).
colorectal polyps (1 paper, 2017). "Our validation in a large set of colorectal polyps and carcinomas showed CD1D downregulation occurs in nearly all CRC, regardless of DNA hypermethylation." (PMID 28931069, 2017).
Cushing syndrome (1 paper, 2022). Cushing's syndrome (CS) encompasses a group of hormonal disorders caused by prolonged and high exposure levels to glucocorticoids that can be of either endogenous (adrenal cortex production) or exogenous (iatrogenic) origin. "In NAFLD mice, the CD1d KO-HFD group was enriched in the sphingolipid signaling pathway, cortisol synthesis and secretion, Cushing syndrome, sphingolipid metabolism pathways, steroid biosynthesis, ovarian steroidogenesis, and aldosterone synthesis and secretion compared with the WT-HFD group." (PMID 35465315, 2022).
cutaneous melanoma (1 paper, 2024). A primary melanoma arising from atypical melanocytes in the skin. "To further delve into the localization of CD1D within the TIME of cutaneous melanoma (CM) and its impact on the interactions between immune cells, we conducted an analysis of the single-cell expression profile in the GSE139249 dataset." (PMID 38279987, 2024).
dementia (1 paper, 2024). Loss of intellectual abilities interfering with an individual's social and occupational functions. "The response to antibody-mediated blocking of CD1d varies between different dementia mouse model systems." (PMID 39720231, 2024). "Thus, the disparate responses to CD1d blocking in AD vs. LBD model systems emphasize the need for further research into the effects of targeting CD1d in multiple forms of dementia." (PMID 39720231, 2024). "In contrast, an interesting study of another form of dementia, Lewy Body Disease (LBD) in α-synuclein transgenic mice (a model for LBD), showed that treatment with anti-CD1d antibodies decreased the numbers of NKT cells and reduced neuroinflammation." (PMID 39720231, 2024).
End Stage Liver Disease (1 paper, 2019). Final stage of a liver disease when the liver failure is irreversible and LIVER TRANSPLANTATION is needed. "CD1d is constitutively expressed on murine hepatocytes, but in humans the situation is less clear: Some authors have shown that CD1d-expression on hepatocytes is pronounced in end-stage liver disease, whereas others that CD1d is downregulated in cirrhotic livers." (PMID 31191516, 2019).
endometriosis (1 paper, 2022). The growth of functional endometrial tissue in anatomic sites outside the uterine body. "The authors performed immunofluorescence staining of iNKT cells for the markers CD3, CD4, and CD1d (counterstained with DAPI) in endometriosis lesions and healthy peritoneum from nine patients." (PMID 35576870, 2022).
enterocolitis (1 paper, 2017). An inflammatory process affecting the small intestine and colon. "Participation of iNKT cells during Salmonella enterocolitis was also analyzed using anti-CD1d antibodies in mice suffering enterocolitis (anti-Cd1d EC group)." (PMID 28944217, 2017).
Fulminant hepatic failure (1 paper, 2021). Hepatic failure refers to the inability of the liver to perform its normal synthetic and metabolic functions, which can result in coagulopathy and alteration in the mental status of a previously healthy individual. "It has been shown that NKT-deficient mice (CD1d-/- and Jα18-/- mice) are more susceptible to fulminant hepatic failure due an marked production of ketone bodies and increased levels of CYP2E1." (PMID 33556084, 2021).
gout (1 paper, 2017). A condition characterized by painful swelling of the joints, which is caused by deposition of urate crystals. "Therefore, deficiency of iNKT cells in CD1d KO mice likely contributes to enhanced gout development." (PMID 29312287, 2017).
Hypercholesterolemia (1 paper, 2023). An increased concentration of cholesterol in the blood. "The chimeras showed similar numbers of APCs, equivalent CD1d expression, and similar circulating iNKT cell numbers pretreatment, while both groups of mice showed characteristic hypercholesterolemia." (PMID 36976644, 2023).
hypersensitivity pneumonitis (1 paper, 2023). Hypersensitivity pneumonitis (HP) is a pulmonary disease with symptoms of dyspnea and cough resulting from the inhalation of an antigen to which the subject has been previously sensitized. "IFN-γ was mainly produced by Gr-1+ neutrophils and played an important pathogenic role since blocking IFN-γ or depleting Gr-1+ neutrophils attenuated hypersensitivity pneumonitis-associated inflammation in CD1d-KO mice." (PMID 37696892, 2023). "However, we found that CD1d-KO mice were more susceptible to Saccharopolyspora rectivirgula-induced hypersensitivity pneumonitis than WT mice and that this was associated with elevated IFN-γ levels in the lung." (PMID 37696892, 2023).
IgA vasculitis (1 paper, 2021). "In patients with IgA vasculitis that had impaired Breg function, the treatment with glucocorticoid prednisolone, promoted an increase in CD5+CD1d+, CD5+CD1d+ IL-10+, and IL-10+ B cell subsets, accompanied by an increase in the serum IL-10 concentration." (PMID 34950041, 2021).
inflammatory skin disease (1 paper, 2022). Inflammatory skin disorders covers a broad category that includes many conditions ranging in severity, from mild itching to grave medical health complications These disorders are common in people of all ages and races. "This mini-review will discuss the immunomodulatory roles of CD1d-restricted NKT cells in various inflammatory skin disorders." (PMID 36119077, 2022). "Roles of CD1d-restricted NKT cells in various inflammatory skin diseases." (PMID 36119077, 2022).
ischemia (1 paper, 2017). A hypoperfusion of the BLOOD through an organ or tissue caused by a PATHOLOGIC CONSTRICTION or obstruction of its BLOOD VESSELS, or an absence of BLOOD CIRCULATION. "This is best exemplified by LPS + IgM-pretreated pan-B cells, which failed to regulate in vivo NKT-1 and protect mice from ischemia-induced AKI despite downregulation of CD1d." (PMID 28878768, 2017).
Laryngopharyngeal Reflux (1 paper, 2021). Back flow of gastric contents to the LARYNGOPHARYNX where it comes in contact with tissues of the upper aerodigestive tract. "Furthermore, H. pylori-associated laryngopharyngeal reflux and the expression of E-cadherin and CD1d (determined by immunohistochemistry) were comparable among the three subgroups." (PMID 34071118, 2021).
leishmaniasis (1 paper, 2021). Infectious disease that is transmitted through the bite of hematophagous female phlebotomine sand flies. "In leishmaniasis, IL-10 secreted by CD5+CD1d+ B cells polarized the Th cell response toward the Th2 phenotype, leading to susceptibility to infection with the parasite in BALB/c mice." (PMID 33750870, 2021).
Lewis Lung carcinoma (1 paper, 2019). "To this end, we demonstrated that that the murine Lewis Lung carcinoma (3LL line, which expresses endogenously CD1d molecules) activated iNKT cells upon treatment with thapsigargin, which was further enhanced upon transduction with lentiviral vectors encoding CD1d molecules." (PMID 31690657, 2019).
lipid-metabolic disorder (1 paper, 2012). "NKT cells have a regulatory role in the pathogenesis of lipid-metabolic disorder including NAFLD through interaction with CD1d on antigen-presenting cells." (PMID 22577564, 2012).
liver disease (1 paper, 2008). "Further, liver disease could be induced by T cell transfer into CD1d-deficient as well as CD1d-sufficient recipients." (PMID 18474357, 2008).
liver failure (1 paper, 2015). A liver disease characterized by the liver losing or has lost all of its function. "Interestingly, Nfil3−/−, but not CD1d−/−, BM lost the ability to rescue Fah−/− mice from liver failure since Nfil3−/− BMT markedly decreased Fah−/− mouse survival and Fah+ BMDH generation after NTBC withdrawal." (PMID 26345133, 2015).
lung fibrosis (1 paper, 2018). "In contrast to CD1d-restricted iNKT cells, the function of CD1a-c-restricted T cells has not been studied either human or mouse models of pulmonary fibrosis." (PMID 30319649, 2018).
lupus nephritis (1 paper, 2025). Glomerulonephritis in the context of systemic lupus erythematosus. "B. fragilis mitigated lupus nephritis symptoms by modulating CD1d and CD86 expression in B cells." (PMID 40534849, 2025).
mediastinal tumors (1 paper, 2019). "Since CD1d expression was very strong and localized predominantly cytoplasmic in ATC cells, we next wanted to assess if this could be used as histopathological tool to help in the differential diagnosis of ATC and other mediastinal tumors." (PMID 31560833, 2019).
metastatic cancer (1 paper, 2011). A carcinoma which has spread from the original site of growth to another anatomic site. "We hypothesized that tumors may acquire a selective advantage by downregulating expression of CD1d, thereby evading iNKT-mediated immune surveillance and promoting metastatic cancer progression." (PMID 21695190, 2011).
metastatic melanoma (1 paper, 2023). A melanoma that has spread from its primary site to another anatomic site. "CD1D differential expression is associated with metastatic melanoma patient survival outcomes from our analysis." (PMID 37077920, 2023). "In conclusion, this study conceptualizes the importance of further investigating therapeutic strategies to restore CD1D expression in metastatic melanoma by targeting epigenetic modulators in the TME." (PMID 37077920, 2023). "We evaluated whether the differential expression of B2M and its correlated genes (CD1D, CD1B, and FCGRT) is associated with poor responses to anti-PD1 in metastatic melanoma." (PMID 37077920, 2023). "Evidence for a new mechanism of ICT resistance is provided by differential expression of β2M/CD1d axis dependent on epigenetic alterations in the TME of metastatic melanoma, which is significantly associated with poor outcomes of metastatic melanoma patients receiving anti-PD1 immunotherapies." (PMID 37077920, 2023). "In addition, glycosphingolipids, such as the ganglioside GD3, have been demonstrated to contribute substantially to the immunogenicity of metastatic melanoma and are presented to NKT cells through CD1d by DCs, coordinating antitumor responses." (PMID 37077920, 2023).
Miscarriage (1 paper, 2022). A pregnancy that ends at a stage in which the fetus is incapable of surviving on its own, defined as the spontaneous loss of a fetus before the 22th week of pregnancy. "We previously reported that activated DCs take up α‐GalCer and activate NKT cells via CD1d and IL‐12, which results in a miscarriage." (PMID 35444491, 2022).
myasthenia gravis (1 paper, 2017). Myasthenia gravis (MG) is a rare, clinically heterogeneous, autoimmune disorder of the neuromuscular junction characterized by fatigable weakness of voluntary muscles. "CD19+CD5+CD1d+ Bregs expression and interleukin (IL)-10 and transforming growth factor (TGF)-β1 secretion in isolated B cells in patients with myasthenia gravis (MG) (n = 10) as compared to healthy controls (HCs) (n = 10)." (PMID 28265257, 2017).
myeloid neoplasm (1 paper, 2010). Proliferation of myeloid cells originating from a primitive stem cell. "With the exception of tumors arising from naturally CD1d+ tissues and cell types such as lymphoid and myeloid neoplasm, the expression pattern of CD1d on malignant cells is largely unknown." (PMID 20593019, 2010).
non-alcoholic steatohepatitis (1 paper, 2023). "Finally, a recent study showed that intrinsic hepatocyte-specific CD1d signaling induced by tyrosine phosphorylation of the CD1d cytoplasmic tail protects against hepatocyte apoptosis in mice with non-alcoholic steatohepatitis induced by an HFD or MCD diet." (PMID 38274786, 2023).
osteoporosis (1 paper, 2021). A condition of reduced bone mass, with decreased cortical thickness and a decrease in the number and size of the trabeculae of cancellous bone (but normal chemical composition), resulting in increased fracture incidence. "To investigate whether NKT‐like or iNKT cells are essential for osteoporosis development, we evaluated the effects of alcohol in Cd1d−/− mice." (PMID 34214248, 2021).
papillary thyroid carcinoma (1 paper, 2024). "The study aimed to investigate the effect of CD1d down-regulation on the proliferation, migration, and apoptosis of papillary thyroid carcinoma cells and explore the underlying mechanism." (PMID 38868316, 2024).
Parkinson disease (1 paper, 2023). A progressive degenerative disorder of the central nervous system characterized by loss of dopamine producing neurons in the substantia nigra and the presence of Lewy bodies in the substantia nigra and locus coeruleus. "Our analysis of B-cell subsets also generated some interesting observations: Parkinson’s disease patients in our cohort had fewer CD1d positive cells than their matched controls." (PMID 36993946, 2023).
Rectal prolapse (1 paper, 2018). Protrusion of the rectal mucous membrane through the anus. "Furthermore, unexpectedly, the incidence of rectal prolapse was significantly increased in Yeti/CD1d KO mice." (PMID 30333822, 2018).
Schistosoma haematobium infections (1 paper, 2022). "Schistosoma haematobium infections lead to increased numbers of NKT cells in the liver and decreased CD1d expression in hepatocytes, which could be associated with CD1d-mediated apoptosis of NKT cells." (PMID 36389166, 2022).
scleroderma (1 paper, 2022). Scleroderma is a rare autoimmune connective tissue disorder characterized by abnormal hardening of the skin and, sometimes, other organs. "Scleroderma patients display significantly higher IL6 production by B cells, and suppression of B cell-derived IL6 was attributed to cell contact between iNKT and CD1d-expressing B cells via the CD1d-TCR axis." (PMID 36119077, 2022).
Sjogren syndrome (1 paper, 2025). An autoimmune disorder in which immune cells attack and destroy the glands that produce tears and saliva. "The sample size is relatively small, and further research is needed to expand the sample size, and the role of CD19+CD5+CD1d+ B cells in the occurrence and development of Sjogren’s syndrome needs further study." (PMID 40678132, 2025).
skin tumor (1 paper, 2025).
streptococcal infection (1 paper, 2017). Any of the several infectious disorders caused by members of streptococcus, a genus of gram positive bacteria belonging to the family Streptococcaceae. "Further studies are required to address the role of NKT cells during these two streptococcal infections and the contribution of CD1d-dependent vs. CD1d-independent activation." (PMID 28706510, 2017).
synucleinopathies (1 paper, 2024). "Taken together, these results suggest that blocking the interactions between NKTs and glial cells with the antibody against CD1d might reduce inflammation in models of synucleinopathy." (PMID 38622654, 2024). "Our interest on CCL4 derives from its ability to attract NKTs among other immune cells, suggesting that in models of synucleinopathy the increased trafficking of some lymphocytic populations to the CNS might be in part mediated by CCL4 and that anti-CD1d immunotherapy might disrupt this process." (PMID 38622654, 2024). "Thus, blocking the APC-NKT interaction with an anti-CD1d antibody reduced some aspects of neuroinflammation and neurodegeneration in models of DLB/PD and might be considered as an alternative immunotherapeutical approach for synucleinopathies of the aging population." (PMID 38622654, 2024).
systemic sclerosis (1 paper, 2018). A chronic disorder, possibly autoimmune, marked by excessive production of collagen which results in hardening and thickening of body tissues. "The CD1d molecule is involved in cardiolipin activation of Vδ1+ T cells in systemic sclerosis." (PMID 29706966, 2018).
T-cell leukemia (1 paper, 2018). A malignant disease of the T-lymphocytes in the bone marrow, thymus, and/or blood. "The human T-cell leukemia cell line Jurkat constitutively expresses the CD1d molecule, and when pulsed with α-GalCer, it operates as an ideal target to examine the intrinsic cytotoxicity of NKT cells." (PMID 30103488, 2018).
T-lymphoblastic lymphoma (1 paper, 2023). The most frequent type of lymphoblastic lymphoma. "Our data also suggest that CAR-iNKT cells would offer additional therapeutic advantages over CAR-T cells in TCRVβ and CD1d co-expressing cases of T cell malignancies such as T lymphoblastic lymphoma, as exemplified by the Jurkat T cell line." (PMID 36936927, 2023).
thyroid (1 paper, 2019). "Also, in this study the correlation between CD1d expression on different thyroid malignancies and its possible prognostic and therapeutic impact was not investigated." (PMID 31560833, 2019).
thyroid tumor (1 paper, 2019). A benign or malignant neoplasm affecting the thyroid gland. "In this study, expression of immunoregulative receptor CD1d and lymphocyte infiltration in different thyroid tumors as well as in healthy tissue were analyzed in order to find new targets for an immunotherapeutic approach." (PMID 31560833, 2019).
varicella (1 paper, 2024). "Prior studies revealed that subjects deficient in NK cells or CD1d molecule experience life-threatening varicella following infection or vaccination." (PMID 38887303, 2024).